KCNJ13 (potassium inwardly rectifying channel subfamily J member 13)
Description:
Inward rectifier potassium channels are characterized by a greater tendency to allow potassium to flow into the cell rather than out of it. Their voltage dependence is regulated by the concentration of extracellular potassium; as external potassium is raised, the voltage range of the channel opening shifts to more positive voltages. The inward rectification is mainly due to the blockage of outward current by internal magnesium. KCNJ13 has a very low single channel conductance, low sensitivity to block by external barium and cesium, and no dependence of its inward rectification properties on the internal blocking particle magnesium.
Synonyms: Kir7.1; Kir1.4; LCA16; SVD
Tractability: Small molecule: it belongs to a druggable protein family. Antibody: UniProt places it where antibodies can reach, with medium confidence; UniProt predicts a signal peptide or a membrane-spanning region; its Gene Ontology location is reachable by antibodies, with medium confidence; the Human Protein Atlas places it where antibodies can reach.
Target class: Inwardly rectifying potassium channel; Potassium channels; Voltage-gated ion channel; Ion channel
Gene: Protein-coding gene on chromosome 2 (232,765,802 to 232,776,565, reverse strand). Ensembl gene ENSG00000115474.
Subcellular location: Membrane; Cell membrane
Subcellular location (Human Protein Atlas): Nuclear membrane; Plasma membrane
Gene Ontology:
Molecular function: inward rectifier potassium channel activity; voltage-gated potassium channel activity
Biological process: intracellular potassium ion homeostasis; regulation of membrane potential; potassium ion import across plasma membrane; potassium ion transport
Cellular component: monoatomic ion channel complex; plasma membrane; membrane
Genetic constraint (gnomAD): Loss-of-function variants: 9 observed, 24.56 expected, observed/expected ratio (o/e) 0.37, 90% interval 0.22 to 0.64. The upper end of that interval is the gene's LOEUF score, 0.64, which puts it in group 2 of 6, group 1 being the genes least tolerant of losing a copy. Missense variants: 332 observed, 460.78 expected, observed/expected ratio (o/e) 0.72, 90% interval 0.66 to 0.79. Synonymous variants: 147 observed, 160.64 expected, observed/expected ratio (o/e) 0.92, 90% interval 0.8 to 1.05.
Gene-disease validity (ClinGen):
ClinGen rates the evidence that KCNJ13 causes each of these diseases.
inherited retinal dystrophy (autosomal recessive): Definitive. An instance of retinal degeneration that is caused by an inherited modification of the individual's genome.
snowflake vitreoretinal degeneration (autosomal dominant): Moderate. Snowflake vitreoretinal degeneration (SVD) is characterized by the presence of small granular-like deposits resembling snowflakes in the retina, fibrillary vitreous degeneration and cataract.
Homologues: Orthologues: chimpanzee KCNJ13 (99% identical), macaque KCNJ13 (99% identical), dog KCNJ13 (97% identical), pig KCNJ13 (96% identical), rabbit KCNJ13 (95% identical), rat Kcnj13 (94% identical), mouse Kcnj13 (93% identical), guinea pig KCNJ13 (90% identical), tropical clawed frog kcnj13 (67% identical), zebrafish kcnj13 (46% identical), Drosophila melanogaster Irk1 (32% identical), Caenorhabditis elegans irk-1 (31% identical), and 4 more. Paralogues in human: KCNJ10 (40% identical), KCNJ15 (37% identical), KCNJ1 (35% identical), KCNJ14 (34% identical), KCNJ2 (34% identical), KCNJ12 (33% identical), KCNJ18 (33% identical), KCNJ6 (31% identical), KCNJ9 (31% identical), KCNJ3 (31% identical), KCNJ4 (30% identical), KCNJ5 (30% identical), and 3 more.
Diseases named in the same sentence as KCNJ13 in open-access papers:
KCNJ13 is named in the same sentence as 44 diseases in open-access papers, as found by Europe PMC text mining. Sharing a sentence is not in itself a finding about the gene and the disease. The quoted sentences say what the papers report.
Leber congenital amaurosis (12 papers, 2013 to 2026). Leber congenital amaurosis (LCA) is a retinal dystrophy defined by blindness and responses to electrophysiological stimulation (Ganzfeld electroretinogram (ERG)) below threshold, associated with severe visual impairment within the first year of life. "Here, we utilized the CRISPR-Cas9 system to generate Kcnj13 mutant mice by zygote injection to verify the pathogenic role of human KCNJ13, mutations of which are thought to cause Leber congenital amaurosis (LCA), an early-onset form of blindness." (PMID 25666713, 2015). "KCNJ13, previously associated with snowflake vitreoretinal degeneration and Leber congenital amaurosis in humans, was evaluated with sequence analysis of nine amplicons encompassing all three exons." (PMID 24019744, 2013). "Similarly, the Kir channel KCNJ13 (Kir7.1) has been reported to be linked to snowflake vitreoretinal degeneration and Leber congenital amaurosis in humans, cleft palate and tracheal tubulogenesis in mice, and pigmentation pattern changes in zebrafish." (PMID 32546498, 2020). "Mutations in KCNJ13 have been linked with two ocular disorders; (i) autosomal recessive Leber congenital amaurosis (LCA, MIM #614186), and (ii) autosomal dominant snowflake vitreoretinal degeneration (SVD, MIM #193230)." (PMID 31647904, 2019). "Mutations in KCNJ13 are associated with two retinal disorders; Leber congenital amaurosis (LCA) and snowflake vitreoretinal degeneration (SVD)." (PMID 30846767, 2019). "Point mutations in the KCNJ13 gene cause autosomal recessive childhood blindness, Leber congenital amaurosis (LCA16), by disrupting Kir7.1 channel function." (PMID 42157932, 2026). "Mutations in the inwardly rectifying potassium channel gene KCNJ13 have been shown to cause both snowflake vitreoretinal degeneration (SVD) and Leber congenital amaurosis (LCA)." (PMID 35096838, 2021). "•A novel fibrovascular proliferation was observed in the retina of two siblings with KCNJ13-Leber congenital amaurosis." (PMID 31647904, 2019). "In another example, postnatal lethality caused by CRISPR/Cas9-mediated disruption of the Leber's congenital amaurosis (LCA)-associated gene potassium inwardly-rectifying channel, subfamily J, member 13 (Kcnj13) was circumvented by analyzing mosaic F0-generation mice." (PMID 30186835, 2018). "Our proteomic data showed significant changes in the levels of proteins for retinitis pigmentosa (RPE65, RP2, MERTK, and RBP3), X-linked retinoschisis (RS1), CRB1-retinal dystrophy (CRB1), Usher syndrome (PCDH15), and Leber congenital amaurosis (RD3 and KCNJ13)." (PMID 36139394, 2022).
retinal degeneration (10 papers, 2015 to 2023). Degeneration of the retina. "In this sense, the downstream pathophysiology of Kcnj13 based retinal degenerations is similar to those of other causes of retinitis pigmentosa, causing photoreceptor or RPE cellular damage and death more directly." (PMID 35096838, 2021). "To test the possibility that off-target effects possibly accompanying Kcnj13 mutations are the cause of the retinal degeneration observed, we performed a series of Surveyor assays on 12 predicted off-target sites." (PMID 25666713, 2015). "Currently, recessive loss-of-function KCNJ13 point mutations are the only known genetic cause of LCA16, disrupting the Kir7.1 channel function and altering RPE physiology, leading to retinal degeneration with progressive vision loss in patients." (PMID 37561581, 2023). "In conclusion, we have used a conditional Kcnj13 knockout mouse model to explore the retinal pathophysiology of KCNJ13 based retinal degenerations, confirming and extending previous observations." (PMID 35096838, 2021). "Our findings suggest that alterations in the RPE and photoreceptor cellular organelles may contribute to KCNJ13-related retinal degeneration and provide a therapeutic target." (PMID 30846767, 2019). "A similar difference between the human and zebrafish phenotypes has been observed previously in the modelling of KCNJ13-LCA, where the homozygous zebrafish kcnj13td15 showed an adult-onset retinal degeneration, contrasting with the early severe phenotype seen in patients." (PMID 34445569, 2021). "A recent study in KCNJ13-KO hiPSC-RPE cells lacking Kir7.1 channel revealed the loss of phagocytic activity as well as the reduced expression of phagocytosis-related genes, which could be a possible cause of retinal degeneration as seen in LCA16 patients." (PMID 32967234, 2020).
vitreoretinal degeneration (9 papers, 2013 to 2025). "For example, mutations in the KCNJ13 gene lead to LCA16, an autosomal recessive disease, and snowflake vitreoretinal degeneration (SVD), an autosomal dominant disease." (PMID 32967234, 2020). "The Kcnj13 gene encodes a member of the inwardly rectifying potassium channel family of proteins and regulates ion transmembrane transport and mutations in Kcnj1 are associated with snowflake vitreoretinal degeneration." (PMID 23421592, 2013). "It is interesting that the region of high embryonic Kcnj13 expression will later form the ciliary body, which might explain the vitreal degeneration seen in snowflake vitreoretinal degeneration patients." (PMID 35096838, 2021).
snowflake vitreoretinal degeneration (7 papers, 2013 to 2025). "Snowflake vitreoretinal degeneration, an autosomal dominant disorder, is linked to the KCNJ13 gene encoding the Kir7.1 inwardly rectifying potassium channel." (PMID 41210874, 2025). "A point mutation in KCNJ13, the gene encoding the protein subunits of the inwardly rectifying potassium channel Kir7.1, is associated with an autosomal dominant Snowflake Vitreoretinal Degeneration (SVD)." (PMID 23977131, 2013).
Blindness (4 papers, 2015 to 2026). Blindness is the condition of lacking visual perception defined as a profound reduction in visual perception. "In this study to delineate the cause of blindness associated with KCNJ13 mutations, we have made several important discoveries that point to an underlying mechanism." (PMID 28878288, 2017). "Thus, we propose that the ERG phenotype in blindness caused by mutations in KCNJ13 is due to a loss of the RPE cell ability to control potassium homeostasis around the photoreceptor outer segment where visual transduction originates." (PMID 28878288, 2017). "Leber congenital amaurosis type 16 (LCA16) is a rare pediatric blindness caused by point mutations in the KCNJ13 gene, a loss of function inwardly rectifying potassium channel (Kir7.1) in the RPE." (PMID 37561581, 2023). "Secondly, we confirmed that the ERG phenotype in KCNJ13-related blindness originated at the RPE cells and is not due to a defective retina." (PMID 28878288, 2017).
Retinal dystrophy (4 papers, 2019 to 2023). Retinal dystrophy is an abnormality of the retina associated with a hereditary process. "Interestingly, genes involved in microphthalmia (VAX1, ALDH1A3, GJA1, and SMOC1) and retinal dystrophies (ADAMTS9, KCNJ13, CA2 and ABCA4) were also selected." (PMID 37479765, 2023).
retinal diseases (3 papers, 2019 to 2023). "•This retinovascular complication should be considered within the clinical spectrum of KCNJ13-related retinal disease." (PMID 31647904, 2019). "Previously, we have described the retinal disease in this zebrafish model which corresponds to the changes seen in patients with KCNJ13-related LCA." (PMID 31647904, 2019).
cleft palate (2 papers, 2015 to 2018). Cleft palate is a fissure type embryopathy that affects the soft and hard palate to varying degrees. "Another cause of early postnatal lethality in null mouse models is a developmental craniofacial alteration leading to cleft palate and a recent study of mouse palatal transcriptome suggests Kcnj13 gene as a potential key regulator of palatal development." (PMID 26402555, 2015).
Tracheomalacia (2 papers, 2020 to 2024). "The Kcnj13–/– mouse bears a lethal phenotype at perinatal age and is affected by severe tracheomalacia, but it is not known if Kir7.1 participates in the anion secretion mechanism and if it relates to the observed phenotype." (PMID 32814712, 2020).
Anxiety (1 paper, 2019). Intense feelings of nervousness, tension, or panic often arise in response to interpersonal stresses. "Conversely, the most downregulated genes observed were KCNJ13 and prolactin (PRL) in the mice that clustered in the high ‘anxiety’ phenotype, which implicate potassium voltage-gated family and oxytocin stimulation." (PMID 31819040, 2019).
cataract (1 paper, 2021). Partial or complete opacity of the crystalline lens of one or both eyes that decreases visual acuity and eventually results in blindness. "Similarly, expression in the embryonic lens might also correlate with all SVD and KCNJ13 related arRP patients developing cataracts by early adulthood." (PMID 35096838, 2021).
cognitive deficits (1 paper, 2018). "Regarding the cognitive deficits, several ion channels, such as Kcnj13 or Kcnj6, and ion channel modulators were deregulated in the present screen." (PMID 30013462, 2018).
glioblastoma (1 paper, 2025). The most malignant astrocytic tumor (WHO grade IV). "Glioblastoma studies included E5 (KCNJ10, KCNN3), E21 (KCNAB2), E26 (KCNE2, KCNJ13), E27 (KCNE4, KCNMB2-AS1), E31 (KCNJ10), E50 (KCND3), and E51 (KCNIP1, KCNJ16, KCNN2)." (PMID 40867621, 2025).
intellectual disabilities (1 paper, 2024). "While many discoveries link their importance to behavioral phenomena, mutations in KCNJ6 (GIRK2) or KCNJ13 (Kir7.1) result in severe cranial-facial malformations along with intellectual disabilities." (PMID 38527087, 2024).
lung carcinoma (1 paper, 2025). "Lung cancer studies included E3 (KCNK1), E8 (KCNK1, KCNN4), E12 (KCNH8, KCNMB2), E23 (KCNU1), E30 (KCNQ5-IT1), E35 (KCNK1), E43 (KCNK6), E49 (KCNN4), 2), E54 (KCNJ13), E63 (KCNK12), and E67 (KCNMB2)." (PMID 40867621, 2025).
nicotine dependence (1 paper, 2023). Physical and psychological dependence on nicotine. "Within this interval, Chrnd and Chrng were previously shown to contribute to nicotine dependence, and Kcnj13 was shown to take part in smooth muscle morphogenesis and trachea development in the mouse respiratory tract." (PMID 37264412, 2023).
retinopathy (6 papers, 2019 to 2026). "We describe the etiology of the LCA16 retinopathy phenotype in three patients from two unrelated families harboring a homozygous KCNJ13 missense mutation (c.431T>C, p.Leu144Pro)." (PMID 42157932, 2026). "Also, RP1L1, PROM1, CRX, CFI and CFB, and KCNJ13 have been linked to retinopathy." (PMID 33330132, 2020). "The fundal appearance was consistent with KCNJ13‐retinopathy and regular fundus examinations are required to mitigate any signs of neovascularization with age." (PMID 32783370, 2020).
KCNJ13 also shares sentences with these, for which no sentence is quoted: retinitis pigmentosa (3 papers); cancer (2); choroid plexus neoplasm (2); Hydrocephalus (2); tumor (2); amyotrophic lateral sclerosis (1); channelopathies (1); cone-rod dystrophy (1); coronary artery disease (1); epilepsy (1); ischemia (1); Leber congenital amaurosis type 16 (1); macular degeneration (1); metastatic carcinoma (1); microphthalmia (1); multiple sclerosis (1); myopia (1); nanophthalmia (1); neurodegenerative disease (1); Obesity (1); papilloma (1); Parkinson disease (1); peripheral nerve injury (1); preeclampsia (1); schizophrenia (1); Usher syndrome (1); X-linked retinoschisis (1).